PRDM5 (PR/SET domain 5)
Description:
Sequence-specific DNA-binding transcription factor. Represses transcription at least in part by recruitment of the histone methyltransferase EHMT2/G9A and histone deacetylases such as HDAC1. Regulates hematopoiesis-associated protein-coding and microRNA (miRNA) genes. May regulate the expression of proteins involved in extracellular matrix development and maintenance, including fibrillar collagens, such as COL4A1 and COL11A1, connective tissue components, such as HAPLN1, and molecules regulating cell migration and adhesion, including EDIL3 and TGFB2. May cause G2/M arrest and apoptosis in cancer cells.
Synonyms: PFM2; BCS2
Tractability: No criterion of Open Targets' tractability assessment is met for any kind of drug.
Gene: Protein-coding gene on chromosome 4 (120,684,919 to 120,923,089, reverse strand). Ensembl gene ENSG00000138738.
Subcellular location: Nucleus
Subcellular location (Human Protein Atlas): Nuclear bodies; Nucleoli; Nucleoplasm
Gene Ontology:
Molecular function: DNA-binding transcription factor binding; DNA-binding transcription repressor activity, RNA polymerase II-specific; protein binding; RNA polymerase II cis-regulatory region sequence-specific DNA binding; sequence-specific DNA binding; transcription cis-regulatory region binding; DNA-binding transcription factor activity; RNA polymerase II transcription regulatory region sequence-specific DNA binding
Biological process: mitotic cell cycle; negative regulation of DNA-templated transcription; negative regulation of transcription by RNA polymerase II; positive regulation of transcription by RNA polymerase II; regulation of extracellular matrix organization
Cellular component: nuclear body; nucleolus; nucleoplasm; nucleus
Genetic constraint (gnomAD): Loss-of-function variants: 49 observed, 69.15 expected, observed/expected ratio (o/e) 0.71, 90% interval 0.56 to 0.9. The upper end of that interval is the gene's LOEUF score, 0.9, which puts it in group 3 of 6, group 1 being the genes least tolerant of losing a copy. Missense variants: 622 observed, 714.12 expected, observed/expected ratio (o/e) 0.87, 90% interval 0.81 to 0.93. Synonymous variants: 237 observed, 241.29 expected, observed/expected ratio (o/e) 0.98, 90% interval 0.88 to 1.09.
Homologues: Orthologues: chimpanzee PRDM5 (99% identical), macaque PRDM5 (99% identical), pig PRDM5 (97% identical), dog PRDM5 (93% identical), rabbit PRDM5 (92% identical), mouse Prdm5 (88% identical), rat Prdm5 (88% identical), guinea pig PRDM5 (88% identical), tropical clawed frog prdm5 (82% identical), zebrafish prdm5 (78% identical). Paralogues in human: ZNF850 (28% identical), ZNF668 (23% identical), ZNF358 (17% identical), ZNF579 (16% identical).
Diseases named in the same sentence as PRDM5 in open-access papers:
PRDM5 is named in the same sentence as 51 diseases in open-access papers, as found by Europe PMC text mining. Sharing a sentence is not in itself a finding about the gene and the disease. The quoted sentences say what the papers report.
brittle cornea syndrome (15 papers, 2012 to 2025). Brittle cornea syndrome is a form of Ehlers-Danlos syndrome characterized by a severe ocular manifestations due to extreme corneal thinning and fragility with rupture in the absence of significant trauma, and progression to blindness. "PRDM5 encodes a zinc finger transcription factor that regulates the expression of collagens and proteoglycans and is best known for its role in brittle cornea syndrome." (PMID 40981152, 2025). "The genes ZNF469 and PRDM5 each produce extracellular-matrix-related proteins that, when mutated, have been shown to result in the development of brittle cornea syndrome." (PMID 38892036, 2024). "Our group has recently identified that two genes, ZNF469 and PRDM5, previously only associated only with brittle cornea syndrome (BCS), are now associated with the development of aortic and arterial aneurysmal diseases (TAADs)." (PMID 38892036, 2024). "PRDM5 mutations have been identified in families with Brittle Cornea Syndrome (BCS), an autosomal-recessive generalized connective tissue disorder." (PMID 38785568, 2024). "PRDM5 mutations in human beings are associated with the development of brittle cornea syndrome (BCS)." (PMID 37629506, 2023). "Loss of PRDM5 is associated with bone morphogenic and developmental defects, and infrequent mutations of PRDM5 have been found in brittle cornea syndrome and neutropenia." (PMID 25613750, 2015). "Recently, mutations in PRDM5 were detected in Brittle Cornea Syndrome (BCS), a connective tissues disease characterized by thinning of the cornea and a wide spectrum of additional symptoms including dermal and skeletal defects." (PMID 22589746, 2012). "In addition, the genes ZNF469 and PRDM5 have been previously associated with joint hypermobility but are mainly characterized by brittle cornea syndrome." (PMID 35886052, 2022). "Of direct relevance, mutations in PRDM5 were recently detected in Brittle Cornea Syndrome." (PMID 22589746, 2012). "Transcriptional control of proteoglycan synthesis and ECM assembly is modulated by proteins produced by genes such as PRDM5 and ZNF469, both of which are associated with brittle cornea syndrome." (PMID 40981152, 2025). "Brittle cornea syndrome is a generalized connective tissue disorder associated with ZNF469 and PRDM5 gene mutations." (PMID 26221552, 2015). "Brittle cornea syndrome is genetically heterogeneous and can be caused by mutations in either ZNF469 (MIM 612078) or PRDM5 (MIM 614161)." (PMID 23680354, 2013). "Brittle cornea syndrome—Initially suspected to be a form of kEDS, brittle cornea syndrome (BCS) was demonstrated to be caused by biallelic pathogenic variants in either the ZNF469 or the PRDM5 gene." (PMID 35205310, 2022). "PRDM5 mutation events contribute to brittle cornea syndrome and neutropenia, however they have not been analysed in cancer types previously." (PMID 25613750, 2015). "Since brittle cornea syndrome is part of a generalized connective tissue disease, ZNF469 and PRDM5 gene products concern the development of extracellular matrix." (PMID 26221552, 2015). "The phenotypic spectrum of brittle cornea syndrome appears in an extremely similar, if not identical manner, in patients with mutations in either ZNF469 or PRDM5, suggesting that the two genes act within the same developmental pathway." (PMID 37443678, 2023).
gastric cancer (11 papers, 2011 to 2025). A primary or metastatic malignant neoplasm involving the stomach. "Additionally, a comprehensive DNA methylation profiling by bisulfite pyrosequencing, performed on normal and cancer samples after successful eradication of Helicobacter pylori, recognized PRDM5 as a risk factor for gastric cancer development." (PMID 32290321, 2020). "Our results showed that aberrant methylation of PRDM5 was associated with its inactivation in multiple tumor cell lines and primary tumors, with the silencing/methylation of PRDM5 in cell lines of gastric cancer (MKN45) and HCC (huH1, Hep3B and HepG2) consistent with previous studies." (PMID 22087297, 2011). "Furthermore, PRDM5 also served as an early diagnostic and prognostic marker, while detection of PRDM5 DNA methylation in gastric secretion may be used as a diagnose method in early gastric cancer." (PMID 35799142, 2022). "miR-409-3p and miR-370-3p levels were similar to let-7d-5p, which has previously been shown to target PRDM5 in gastric carcinoma cell lines, including AGS, to promote cell proliferation, migration, invasion and reduce apoptosis." (PMID 40674434, 2025). "Previous studies have shown that ectopic expression of PRDM5 can inhibit the proliferation of gastric cancer, nasopharyngeal cancer, and brain glioma cells." (PMID 35799142, 2022). "In the nucleus of gastric cancer cells, PRDM5 is rarely expressed, while in the nucleus of normal tissues adjacent to cancer, PRDM5 is almost always expressed." (PMID 34659579, 2021). "This is the first study to show that a particular subgroup of colorectal cancer has a comparably high rate of PRDM5 methylation as previously found in other cancers such as lung, breast, liver and gastric cancer." (PMID 25613750, 2015). "A mammalian expression vector encoding full-length PRDM5 was transfected into nasopharyngeal, esophageal and gastric cancer cell lines with completely methylated and silenced PRDM5 (HONE1, KYSE140 and MKN28)." (PMID 22087297, 2011). "Among them, PRDM5 was found to be frequently methylated and silenced in gastric cancer." (PMID 34659579, 2021). "In gastric cancer, whether PRDM5 plays a role in tumor inhibition through these possible pathways still needs further verification." (PMID 34659579, 2021). "Moreover, PRDM5 expression is undetectable in colorectal cancer and gastric cancer due to DNA methylation or trimethylation of Lys27 of histone H3 (H3K27) and PRDM5 overexpression significantly inhibits the colony formation of gastric cancer cells." (PMID 27485778, 2016). "Collectively, our findings suggested that hsa-let-7d-5p promoted the development of GC by targeting PRDM5, indicating that hsa-let-7d-5p could be a promising therapeutic molecule for the treatment of gastric cancer." (PMID 35847370, 2022). "To evaluate the correlation between PRDM5 expression and patients' survival, we observed RPDM5 expression that performed IHC and analyzed in 162 gastric cancer patients." (PMID 34659579, 2021). "The study found that six genes (MINT25, RORA, GDNF, ADAM23, PRDM5, MLF1) presented differential methylation between gastric cancer and normal mucosa in the training and test population." (PMID 32489454, 2020). "We found that The expression of PRDM5 in gastric cancer tissues was lower than that in paracancer tissues, and only a few GC tissues showed no significant change in the expression of PRDM5." (PMID 34659579, 2021). "Of note, PRDM5 promoter methylation was detected in both primary colorectal and gastric cancers but not in noncancerous tissue specimens collected from areas adjacent to the tumors." (PMID 32290321, 2020).
breast cancer (8 papers, 2015 to 2025). A primary or metastatic malignant neoplasm involving the breast. "It has been reported that PRDM5 expression is reduced in human breast cancer, ovarian cancer, and liver cancer, and reintroduction of PRDM5 into ovarian cancer cells causes G2/M cell cycle arrest and apoptotic cell death." (PMID 27485778, 2016). "In particular, SIX1 has been shown to induce EMT and metastasis in breast tumors and implicated in TGF-β regulation of collagen deposition leading to hampered immune infiltration and survival in cancer, while PRDM5 has been linked to pro-metastatic production of collagen in breast cancer." (PMID 39939916, 2025). "We found that for seven HMTs (KMT2C, SETDB2, SETD2, SETMAR, PRDM1, PRDM5, and PRDM8), copy number amp/gain or deletion was significantly associated (p<0.05) with shorter survival in breast cancer patients." (PMID 25537518, 2015). "PRDM5, a known tumor suppressor and epigenetic regulator, is often silenced in breast cancer." (PMID 40862714, 2025). "The reason why PRDM5 works in opposite directions between melanoma and epithelial tumors, such as breast cancer, ovarian cancer, and liver cancer, may be ascribed to its unique function in transcription regulation." (PMID 27485778, 2016). "Upregulation of NNMT maintains the cancer-associated fibroblast phenotype, activates the PRDM5/COL1A1 axis, and promotes tumor metastasis in gastric cancer and breast cancer (BC)." (PMID 39399490, 2024). "PRDM5/PFM2 is a zinc finger protein acting as an epigenetic modifier known as a tumor suppressor; it is frequently silenced/downregulated/inactivated by methylation in multiple carcinoma lines, such as NPC, ESCC, GC, and HCC and ovarian, cervical, and breast cancers." (PMID 37834160, 2023). "Furthermore, PRDM5 overexpression may induce cell cycle arrest at G2/M phase and apoptotic cell death in MDAH2774 and BG1 ovarian cancer cell lines, MB435 breast cancer cells, and Ha22T hepatocellular carcinoma cells." (PMID 27485778, 2016).
cervical carcinoma (4 papers, 2011 to 2022). A carcinoma arising from either the exocervical squamous epithelium or the endocervical glandular epithelium. "Previous studies have found that PRDM5 expression is lower in multiple cancer species than in adjacent tissues, including breast, ovarian, liver, lung, colon cancers, and cervical cancers, and that silencing or downregulation of PRDM5 is often caused by DNA methylation." (PMID 35799142, 2022). "Silencing PRDM5 by methylation in tumor cell lines leads to changes in various tumors including nasopharyngeal, esophageal, gastric, hepatocyte, and cervical cancer." (PMID 35799142, 2022). "It is worth noting that although PRDM5 expression is reduced in most tumors, such as lung cancer, cervical cancer, prostate cancer, glioma and other tumors 21-24." (PMID 34659579, 2021). "Here, we studied the epigenetic abnormality and tumor suppressive functions of PRDM5 in multiple common tumors including nasopharyngeal, esophageal, gastric, hepatocellular and cervical cancers." (PMID 22087297, 2011). "Results revealed that PRDM5 was frequently downregulated or silenced in cell lines of nasopharyngeal, esophageal, gastric, hepatocellular and cervical carcinomas, but readily detected in immortalized normal epithelial cell lines." (PMID 22087297, 2011).
lung carcinoma (4 papers, 2016 to 2024). "However, target genes regulated by PRDM5 in lung cancer and its potential mechanism are poorly defined." (PMID 36127737, 2023). "Studies have shown that the PRDM2, PRDM5, and PRDM16 promoters in lung cancer cells are methylated, resulting in suppressed expression." (PMID 39468462, 2024).
melanoma (4 papers, 2016 to 2021). A malignant, usually aggressive tumor composed of atypical, neoplastic melanocytes. "In the future, it is worthwhile to delineate the specific mechanism underlying PRDM5‐mediated JNK expression as well as PRDM5‐induced progression of melanoma." (PMID 27485778, 2016). "The underlying molecular mechanism for PRDM5‐regulated melanoma progression was identified to be related to JNK signaling pathway." (PMID 27485778, 2016). "In a murine melanoma model, it was demonstrated that PRDM5 (PRDI-BF1 and RIZ domain-containing) promoted melanoma proliferation and invasion through the upregulation of JNK." (PMID 32252279, 2020). "In conclusion, PRDM5 silencing significantly reduced the proliferation, migration, and invasion potentials of murine melanoma cells." (PMID 27485778, 2016). "In summary, PRDM5 overexpression is able to enhance the proliferation and migratory potentials of murine melanoma cells." (PMID 27485778, 2016). "Compared with the control group, the number of metastatic foci was significantly reduced in mice injected with PRDM5 knock‐down cells, suggesting that PRDM5 silencing impairs the metastatic potential of melanoma cells in vivo." (PMID 27485778, 2016). "In vivo study also showed that PRDM5 silencing significantly inhibited the growth and metastasis of melanoma in mice." (PMID 27485778, 2016). "Although our study for the first time showed that PRDM5 acts as an important promoter in the progression of malignant melanoma, it is unclear how PRDM5 works." (PMID 27485778, 2016). "On day 11, the tumor size in siPRDM5 group was significantly smaller than in siCTL group and the tumor weight in siPRDM5 group was also significantly lighter than in siCTL group, indicating that PRDM5 silencing inhibits the growth of melanoma cells in vivo." (PMID 27485778, 2016). "Consistently, when PRDM5 expression was silenced by siRNA in melanoma cells, JNK expression and activation were also reduced." (PMID 27485778, 2016). "Next, wound healing assay and transwell migration and invasion assays were employed to examine the influence of PRDM5 gene silencing on the migration and invasion of melanoma cells." (PMID 27485778, 2016). "Of interest, our results showed that PRDM5 overexpression significantly enhanced the proliferation, migration, and invasion of murine melanoma B16F10 cells, and silencing of PRDM5 expression was found to reduce the proliferation and metastasis of these cells." (PMID 27485778, 2016). "Due to the important roles of PRDM5 in the progression of melanoma, it will become an attractive target for the molecular therapy of melanoma." (PMID 27485778, 2016). "The effect of PRDM5 overexpression on the migration potential of melanoma cells was also evaluated by wound healing assay." (PMID 27485778, 2016). "Then, the growth capacity of these cells was investigated by MTT assay and results showed that PRDM5 overexpression significantly enhanced the growth of melanoma cells." (PMID 27485778, 2016). "PRDM5 silencing significantly reduced the growth of melanoma cells." (PMID 27485778, 2016). "However, in a pilot study, our results showed that disruption of PRDM5 expression by insertional mutagenesis mediated by pDisrup 8, a specifically designed retroviral vector, reduced the migration potential of murine melanoma B16F10 cells (unpubl." (PMID 27485778, 2016). "In vivo experiments revealed that PRDM5 silencing greatly inhibited the melanoma progression." (PMID 27485778, 2016). "We conclude that PRDM5 promotes the proliferation and invasion of murine melanoma cells through up‐regulating JNK expression and strategies targeting PRDM5 may be promising for the therapy of melanoma." (PMID 27485778, 2016). "In summary, our results indicated that PRDM5 potentiates the progression of murine melanoma through up‐regulating JNK expression, indicating that PRDM5 may function as an oncogene in melanoma." (PMID 27485778, 2016).
melanoma (continued). "In our study, effect of PRDM5 on murine melanoma cells was determined and results showed that PRDM5 overexpression significantly promoted proliferation, migration, and invasion of murine melanoma B16F10 cells." (PMID 27485778, 2016). "In this study, we determined the function of PRDM5 in the pathogenesis of melanoma." (PMID 27485778, 2016). "PRDM5 might activate a set of genes favoring cell proliferation and migration in melanoma cells, whereas it inactivates another set of genes in epithelial tumors." (PMID 27485778, 2016). "Surprisingly, the role of PRDM5 in melanoma is different from that reported in other studies." (PMID 27485778, 2016). "data) and PRDM5 could exert effects in melanoma cells distinct from those in other cell types, but the specific mechanism is needed to be further studied." (PMID 27485778, 2016). "Moreover, PRDM5 potentiated the progression of murine melanoma via up‐regulating JNK expression." (PMID 27485778, 2016). "However, PRDM5 could also play an opposite role in melanoma." (PMID 32290321, 2020). "Our results showed that PRDM5 overexpression in B16F10 murine melanoma cells induced up‐regulation of JNK expression, and PRDM5 silencing reduced JNK expression." (PMID 27485778, 2016). "However, the role of PRDM5 in murine melanoma remains largely unknown." (PMID 27485778, 2016). "Of note, we further evaluated the effects of PRDM5 on the in vitro proliferation and migration of human melanoma HTB‐72 cells and murine melanoma B16F0 cells." (PMID 27485778, 2016). "Indeed, the results of a recent study showed that Prdm5 potentiated the progression of murine melanoma through upregulating JNK expression, suggesting that PRDM5 may function as an oncogene in this malignancy." (PMID 32290321, 2020). "However, no study has been conducted to investigate the role of PRDM5 in the pathogenesis of melanoma." (PMID 27485778, 2016). "This indicates that the effects of PRDM5 in melanoma do not vary between species." (PMID 27485778, 2016).
colon cancer (3 papers, 2012 to 2022). "PRDM5 is a tumor suppressor gene, and loss of this gene is related with colon cancer tumorigenesis." (PMID 35178443, 2022). "MGLL is characterized as a direct PRDM5 target in human colon cancer cells and in Prdm5 mutant mouse intestines." (PMID 35178443, 2022).